LECT2 (leukocyte cell derived chemotaxin 2)
Diseases named in the same sentence as LECT2 in open-access papers (continued):
Sharing a sentence is not in itself a finding about the gene and the disease.
hepatocellular carcinoma (18 papers, 2014 to 2024). A malignant tumor that arises from hepatocytes. "For sustained LECT2 production in HCC, we generated a recombinant Ad encoding LECT2 (Ad-LECT2) for gene delivery study in rats bearing established Novikoff hepatoma." (PMID 36055405, 2022). "LECT2 deficiency fosters the accumulation of pejorative inflammatory monocytes harboring immunosuppressive properties and strong tumor-promoting potential in hepatocellular carcinoma." (PMID 37600770, 2023). "Furthermore, Lect2 has been shown to be a mediator of the β-catenin inflammatory response during hepatocellular carcinoma and loss of this tumour suppressor results an increase in tumorigenesis." (PMID 30559928, 2018). "In hepatocellular carcinoma (HCC), LECT2 expression is negatively associated with the immune infiltration of monocyte, B cells, neutrophil, and myeloid dendritic cells and positively associated with hematopoietic stem cells and CD8 naive T cells." (PMID 36969200, 2023). "The keywords in the first five clusters indicate that LECT2 research has achieved more significant results in human hepatocellular carcinoma, systemic inflammation, chemotactic factor, selenoprotein p and JNK-dependent inhibition." (PMID 38881894, 2024). "Clinical and animal model evidence supports a tumor-suppressive role of LECT2 in cancer, particularly hepatocellular carcinoma." (PMID 38177412, 2024). "Above all, immunohistochemical analysis confirmed that Ad-LECT2 therapy significantly diminished the β-catenin level in rat hepatoma tissues (∗∗p < 0.01)." (PMID 36055405, 2022). "Exogenous LECT2 potentially repressed CSCs properties such as cell self-renewal and drug efflux in hepatoma cells accompanied with the downregulation of CSCs markers." (PMID 36055405, 2022). "After confirming the transgenes expression in hepatoma cells by immunoblot analysis, the influence of LECT2 gene delivery on the oncogenic behaviors of hepatoma cells was explored." (PMID 36055405, 2022). "To determine the effect of LECT2 on innate immune responses in hepatocytes, we established a human hepatocellular carcinoma cell line overexpressing LECT2 (HepG2-LECT2 cells) by using a lentivirus expression system." (PMID 35676290, 2022). "It was shown that the CD31+ blood vessels were significantly reduced in Ad-LECT2–treated hepatoma compared with control groups." (PMID 36055405, 2022). "In the current study, the biological function of LECT2 in HCC, especially hepatic CSCs, was investigated, and the therapeutic efficacy of intratumoral LECT2 gene delivery by adenovirus (Ad) was evaluated in the immune-competent orthotopic hepatoma model." (PMID 36055405, 2022). "By using an array of human hepatoma cell lines with different differentiation statuses, immunoblot analysis revealed that the LECT2 expression was reduced in the poorly differentiated hepatoma cells than in the well-differentiated ones." (PMID 36055405, 2022). "This study is the first to provide a comprehensive and detailed analysis of the role of LECT2 in HCC and to show that LECT2 is a new potential diagnostic and prognostic biomarker for hepatocellular carcinoma." (PMID 36160006, 2022). "Leukocyte cell-derived chemotaxin 2 (LECT2) acts as a tumor suppressor in hepatocellular carcinoma (HCC)." (PMID 36055405, 2022). "In the animal experiment, we demonstrated that Ad-LECT2 gene therapy showed excellent therapeutic efficacy in immune-competent orthotopic hepatoma." (PMID 36055405, 2022). "Since CD44+/CD133+ cells account for an important subpopulation of hepatic CSCs, immunofluorescent analysis further confirmed that LECT2 therapy significantly decreased the CD44+/CD133+ hepatic CSCs in Novikoff hepatoma (∗∗p < 0.01)." (PMID 36055405, 2022). "In rat Novikoff hepatoma model, immunoblot analysis showed LECT2 protein level in rat N1-S1 HCC cells was lower than that in rat Clone 9 hepatocytes." (PMID 36055405, 2022).
hepatocellular carcinoma (continued). "In terms of cancer, LECT2 has been shown to act as a tumor suppressor in multiple cancers, such as hepatocellular carcinoma, non-small cell lung cancer, and intestinal cancer." (PMID 33937262, 2021). "In human hepatocellular carcinoma, low LECT2 expression is correlated with advanced histological grade and inflammatory infiltrates." (PMID 31310065, 2019). "Lect2 has a key role in several pathological conditions including rheumatoid arthritis, renal amyloidosis, hepatocellular carcinoma, liver injury and sepsis, where its main activity is thought to be in modulating the inflammatory response." (PMID 30559928, 2018). "Moreover, flow cytometry analysis revealed that LECT2 gene delivery significantly increased the ratio of sub-G1 apoptotic cells in cultured N1-S1 hepatoma cells." (PMID 36055405, 2022). "The effect of LECT2 on EMT of hepatoma cells was further studied in this research." (PMID 36055405, 2022). "Using functional assays, we also found LECT2 was capable of suppressing oncogenic behaviors such as cell proliferation, anchorage-independent growth, migration, invasiveness, and epithelial-mesenchymal transition in hepatoma cells." (PMID 36055405, 2022). "Since LECT2 was reported to antagonize MET receptor activation in hepatocellular carcinoma and non-small cell lung cancer, we speculated that LECT2 might regulate FOXM1 signaling by targeting MET." (PMID 33937262, 2021). "LECT2 also curtails the advancement of hepatocellular carcinoma (HCC) by interacting with iNKT cells, thereby obstructing β-catenin-induced inflammation." (PMID 38155961, 2023). "Therefore, LECT2 is also closely associated with a variety of liver diseases, such as non-alcoholic fatty liver disease (NAFLD), and liver fibrogenesis, and hepatocellular carcinoma." (PMID 36160006, 2022). "Generally, LECT2 expressions were strikingly down‐regulated in human HCC (hepatocellular carcinoma) samples (78.4%, 40/51), relative to normal liver tissues." (PMID 35656863, 2022). "New research has uncovered that in the pathogenesis of hepatocellular carcinoma (HCC), LECT2 can improve the tumor microenvironment, and prevent vascular invasion and metastasis in HCC." (PMID 38881894, 2024). "We demonstrate LECT2 overexpression significantly promoted cell apoptosis and reduced neovascularization/CSC expansion in rat hepatoma tissues." (PMID 36055405, 2022). "This indicates that SPP2, LECT2, CPS1, and Ribokinase exert tumor suppressive effects in hepatocellular carcinoma." (PMID 31849319, 2019). "In the article titled “LECT2 Controls Inflammatory Monocytes to Constrain Growth and Progression of Hepatocellular Carcinoma”, the authors analyze how LECT2 influences the progression of HCC and suggest that LECT2 could be a beneficial immunotherapy choice for HCC." (PMID 38881894, 2024). "Likewise, immunohistochemical analysis showed that intratumoral LECT2 gene delivery significantly inhibited the expression of CD133 and CD44 in Novikoff hepatoma tissues." (PMID 36055405, 2022). "SPP2 was co-expressed with LECT2, CPS1, and Ribokinase in hepatocellular carcinoma." (PMID 31849319, 2019). "However, there are still no studies with a comprehensive analysis of the role of LECT2 in hepatocellular carcinoma (HCC)." (PMID 36160006, 2022). "Furthermore, exogenous LECT2 or Ad-LECT2 administration effectively suppressed anchorage-independent growth, cell migration, and cell invasiveness companied with EMT inhibition in both rat and human hepatoma cells." (PMID 36055405, 2022).
Hepatic steatosis (15 papers, 2016 to 2025). Steatosis is a term used to denote lipid accumulation within hepatocytes. "While the association of LECT2 overexpression with metabolic syndrome, fatty liver disease and cancer is well established, very few studies have investigated the role of this hepatokine in adipogenesis." (PMID 35409319, 2022). "Even with short term HFD feeding, where body weight and liver steatosis were comparable between wild-type and Lect2 deficient mice, Lect2 deficient mice were protected from the M1-like shift of macrophages and induction of inflammatory genes in the liver." (PMID 33436955, 2021). "In vitro studies showed that inhibition of hepatic LECT2 expression in mice attenuated HFD-induced hepatic steatosis, whereas hepatic overexpression of LECT2 aggravated HFD-induced hepatic steatosis and inflammation." (PMID 36397950, 2022). "In the present study, hepatic expressions of the LECT2 gene was upregulated in tissue samples from patients with hepatic steatosis and inflammation, and both steatosis and inflammation were positively correlated with LECT2 gene expression." (PMID 33436955, 2021). "Its synthesis is highly sensitive to changes in dietary fat content as well as to the severity of hepatic steatosis; indeed, LECT2 has been shown to be dysregulated in the presence of hepatic steatosis, and its upregulation is associated with advanced stages of human liver fibrosis." (PMID 39409124, 2024). "In patients with NASH, the LECT2 levels were correlated with liver steatosis (ρ = 0.601)." (PMID 37957316, 2024). "Moreover, LECT2 contributed to M1‐like macrophage phenotype and the M1/M2 ratio, making a linkage from liver steatosis to hepatic inflammation in NASH." (PMID 35656863, 2022). "Based on the previous and current findings, we propose that hepatic steatosis and inflammation progress simultaneously during NASH development because liver fat accumulation induces LECT2, which drives inflammation." (PMID 33436955, 2021). "As LECT2 induces SREBP-1c cleavage, and lipid accumulation, DPP4i-treated mice showed improved hepatic steatosis." (PMID 33173107, 2020). "Recent evidence in mice demonstrated that dipeptidyl peptidase-4 (DPP-4) inhibitors could improve the degree of hepatic steatosis and IR through AMPK-dependent and JNK-dependent inhibition of LECT2 expression." (PMID 38297351, 2024). "Hwan-Jin Hwang and Tae Woo Jung have discovered that in the development of hepatic steatosis, adenosine 5’-monophosphate (AMP)-activated protein kinase (AMPK) and JNK mechanisms could play a role in regulating LECT2 expression and inducing liver inflammation." (PMID 38881894, 2024). "Gemigliptin (a novel DPP4 inhibitor) might mitigate hepatic steatosis and IR, suggesting a direct protective effect on NAFLD progression, which inhibits the expression of LECT2 through AMPK-dependent and JNK-dependent mechanisms." (PMID 36267567, 2022).
amyloidosis (14 papers, 2015 to 2026). A disorder characterized by the localized or diffuse accumulation of amyloid protein in various anatomic sites. "So far, the association of LECT2 and renal function has even been reported many times, but only in the context of one condition—leucocyte chemotactic factor 2 amyloidosis (ALECT2)." (PMID 38137613, 2023). "It is an acquired form of amyloidosis, although genetic factors also play a role-people with the I40V LECT2 gene polymorphism are particularly prone to ALECT2." (PMID 38137613, 2023). "Leukocyte chemotactic factor 2-associated (ALECT2) amyloidosis is one of the recently reported types of amyloidosis, which is caused by the extracellular deposition of leukocyte chemotactic factor 2 (LECT2)." (PMID 36059556, 2022). "The etiology of ALECT2 amyloidosis remains unclear and may be associated with LECT2 protein deposition in localized tissues." (PMID 40443630, 2025). "With access to novel diagnostic approaches, advances in biochemical tissue analysis have identified leukocyte chemotactic factor 2 (LECT2) as a novel subtype of amyloid causing kidney disease, primarily among Hispanic persons in the Southwest region of the United States." (PMID 39636884, 2024). "This fact can be associated with LECT2 amyloidosis, although it should be verified whether in the geriatric population there is indeed a widespread accumulation of LECT2 with the progression of aging or whether it is rather a marker of general deterioration of renal function." (PMID 38137613, 2023). "ALECT2 amyloidosis is a rare systemic disease characterized by the pathological deposition of leukocyte cell-derived chemotaxin-2 (LECT2) as amyloid fibrils, primarily affecting the kidneys and liver." (PMID 41965342, 2026). "Current research on LECT2 is focused on cell-derived chemotaxin 2, angiogenesis, leukocyte chemotactic factor 2 amyloidosis (ALECT2), diagnosis, and biliary atresia (BA), marking an emerging period of study." (PMID 38881894, 2024). "Analysis of LECT2 gene sequence in peripheral blood samples can serve as a predictive tool for LECT2 amyloidosis." (PMID 38881894, 2024). "No mutations in the LECT2 gene have been identified in patients with ALECT2 amyloidosis, but most of these patients are homozygous for the G allele encoding valine at position 40 in the mature protein." (PMID 40443630, 2025). "Their findings lay the foundation for further research into the effects of LECT2 on amyloidosis." (PMID 38881894, 2024). "In addition, the misfolding LECT2 leads to the amyloidosis of several crucial tissues (kidney, liver, and lung, etc.)by inducing the formation of insoluble fibrils." (PMID 36969200, 2023). "Besides its soluble functioning as a cytokine or hepatokine, LECT2 also exists in the form of amyloidosis (aLECT2) and is involved in renal and hepatic amyloid lesions." (PMID 36969200, 2023). "The mutation or genetic variations of LECT2 are responsible for the formation of aLECT2, while the misfolding LECT2, which leads to insoluble fibrils aggregated in cells and tissues, might be the potential pathogenesis of LECT2-mediated amyloidosis." (PMID 36969200, 2023). "Genetic analysis of the LECT2 gene in patient 1 revealed a codon change from ATC to GTC at position 172 [c.172A>G (p.Ile58Val; NM_002302)], which is a common polymorphism (SNP rs31517) in all ALECT2 amyloidosis patients." (PMID 35572989, 2022). "In addition, leukocyte chemotactic factor 2 amyloidosis (ALECT2) is a recently described type of amyloidosis secondary to LECT2, a protein synthesized mainly by the liver and a chemotactic factor for neutrophils." (PMID 36197414, 2022). "Genetic analysis of this patient revealed a single base transversion from A to G at position 172 of the LECT2 gene [c.172A>G (p.Ile58Val; NM_002302)], this is a common polymorphism (SNP rs31517) that are thought to be present in all ALECT2 amyloidosis patients." (PMID 35572989, 2022).
amyloidosis (continued). "Although the underlying pathogenesis remains unknown, LECT2 overexpression might be responsible for renal LECT2 amyloidosis." (PMID 32764719, 2020). "Indeed, in a case series of ALECT2, none of 72 patients had a family history of amyloidosis and no pathogenic variants were detected in LECT2 in the 16 patients analyzed at the molecular level." (PMID 36197414, 2022). "Additionally, hepatokine LECT2 amyloidosis has been related to portal hypertension." (PMID 28924246, 2017). "In Leukocyte chemotactic factor-2 amyloidosis (ALECT2), empirical data showed that the SC of LECT2 is generally low, and is almost impossible to be the highest." (PMID 35418036, 2022). "In addition, LECT2 was not identified in all other amyloidosis other than ALECT2 type and non-amyloid nephropathies." (PMID 35418036, 2022).
metabolic syndrome (13 papers, 2017 to 2025). A cluster of metabolic risk factors for CARDIOVASCULAR DISEASES and TYPE 2 DIABETES MELLITUS. "Plasma LECT2 levels were positively correlated with visceral fat area and its differential expression was associated with metabolic and dyslipidemia." (PMID 34899846, 2021). "It was also reported that LECT2 expression is increased in non-alcoholic fatty liver disease in association with metabolic syndromes such as abdominal obesity and lipid metabolism." (PMID 31480179, 2019). "In model 2, plasma LECT2 levels were associated with the presence of dyslipidemia even after adjustment for VFA, whereas the association between VFA and dyslipidemia was attenuated after adjustment for LECT2 levels." (PMID 28278265, 2017). "Finally, although the present cross-sectional study demonstrated LECT2 was a significant predictor of dyslipidemia, it is still unclear whether LECT2 is also associated with development of dyslipidemia and the incidence of coronary heart diseases." (PMID 28278265, 2017). "MS can be a strong therapeutic strategy to halt the overproduction of LECT2 if this insight is confirmed as the true phenomenon of metabolic syndrome." (PMID 37957316, 2024). "In humans, visceral fat area has been identified as the strongest predictor of plasma LECT2, which is a potential biomarker linking visceral obesity to dyslipidemia." (PMID 39409124, 2024). "We can apply circulating LECT2 levels as a predictive marker of metabolic syndrome on the basis of previous relationships between LECT2 and MAFLD." (PMID 37957316, 2024). "In a study of 200 people in Japan, serum LECT2 levels correlated positively with some clinical features of metabolic syndrome, namely body mass index, waist circumference, systolic blood pressure, serum selenoprotein P levels, and hemoglobin A1c blood levels." (PMID 38137613, 2023). "Our data also indicate that LECT2 is a potential biomarker linking visceral obesity to dyslipidemia." (PMID 28278265, 2017). "VFA was the strongest predictor of plasma LECT2 that is a potential biomarker linking visceral obesity to dyslipidemia." (PMID 28278265, 2017). "In model 1, both plasma LECT2 levels and VFA were significantly associated with the presence of dyslipidemia and metabolic syndrome, respectively." (PMID 28278265, 2017). "The results of the logistic regression analyses also demonstrated that LECT2 was the independent predictor of dyslipidemia." (PMID 28278265, 2017). "We examined circulating plasma LECT2 levels in the subjects with non-alcoholic fatty liver disease (NAFLD) or metabolic syndrome." (PMID 28376109, 2017). "In conclusion, circulating LECT2 levels were significantly associated with NAFLD and metabolic syndrome mainly by mediating dyslipidemia and abdominal obesity." (PMID 28376109, 2017). "However, the statistical significance was attenuated after adjusting for serum triglyceride, HDL-C, LDL-C levels and waist circumference, suggesting that LECT2 might be associated with the development of NAFLD through mediation of dyslipidemia and abdominal obesity." (PMID 28376109, 2017). "Similarly, a Korean study demonstrated that the plasma LECT2 levels are higher in individuals with both NAFLD and metabolic syndrome, with strong associations observed with abdominal obesity, serum AST/ALT level, lipid profiles, and hsCRP." (PMID 40284206, 2025). "On the other hand, LECT2 secretion from visceral adipose tissue may have an effect on the onset and progress of metabolic syndrome including NASH." (PMID 37957316, 2024). "In addition, circulating LECT2 level had a significant positive correlation with the number of metabolic syndrome components in the total subjects." (PMID 28376109, 2017). "Furthermore, we also indicated that plasma LECT2 was a potential biomarker linking visceral fat accumulation to dyslipidemia." (PMID 28278265, 2017).